CRP (C-reactive protein)
Diseases named in the same sentence as CRP in open-access papers (continued):
Sharing a sentence is not in itself a finding about the gene and the disease.
congestive heart failure (168 papers, 2005 to 2025). Failure of the heart to pump a sufficient amount of blood to meet the needs of the body tissues, resulting in tissue congestion and edema. "Elevated CRP is typically linked to increased morbidity and mortality in both acute and chronic heart failure." (PMID 40894478, 2025). "Elevated C-reactive protein (CRP) is typically linked to increased morbidity and mortality in both acute and chronic heart failure." (PMID 40894478, 2025). "Background and Objectives: In this study, we aimed to investigate the prognostic value of the C-reactive protein to albumin ratio (CAR) for all-cause mortality in patients with chronic heart failure with reduced ejection fraction (HFrEF)." (PMID 38541167, 2024). "A recent MR study on East Asian people found suggestive evidence of a causal relationship between CRP and congestive heart failure in their IVW approach, which is consistent with the findings of our analysis, though conducted on a different community." (PMID 36882679, 2023). "In chronic heart failure, the level and pattern of increase in NTproBNP, Troponin T and CRP is shown to be associated with adverse prognosis." (PMID 33536059, 2021). "Furthermore, studies have demonstrated the association between CRP level and the prognosis of atherosclerotic disease, congestive heart failure (CHF), atrial fibrillation, myocarditis, aortic valve disease, and heart transplantation." (PMID 40330210, 2025). "The risk score equation for Model 2 was: risk score = – 8.428 + 0.043 (age) + 0.915 (if congestive heart failure was positive) + 0.778 (if previous AIS/TIA was true) + 0.207 (NIHSS score) + 0.008 (CRP) + 0.016 (BNP) + 0.966 (if cortical infarction was positive)." (PMID 36313507, 2022). "It is of note that the rare recessive genotype rs1800947 CC of the CRP gene was recently found to have a significant influence on CRP concentration, mortality and depressive symptoms in chronic heart failure patients; the highest risk CC carriers had the highest hs-CRP levels." (PMID 31788733, 2019). "Measuring the CRP values in 84 patients with chronic heart failure, after a mean follow-up period of 42 months, they observed that NIDCM patients with high plasma CRP values have a poor prognosis, independent of other parameters." (PMID 34073616, 2021). "Our results indicate that current smokers have an increased SIR at admission, as indicated by their CRP levels, and that this is modulated by age, the presence of chronic heart failure, and by the prior use of ICS or OCS therapy." (PMID 32906593, 2020). "History of congestive heart failure, albumin level, C-reactive protein level, and age at dialysis initiation were the most important factors affecting the prediction for first-year mortality in both model 1 and model." (PMID 33118948, 2020). "They took into account highly sensitive CRP (hs-CRP), related to CVD and the N-terminal pro-BNP (NT-proBNP), diagnostic for congestive heart failure." (PMID 29036907, 2017). "We evaluated ST2 and CRP as prognostic markers in 178 patients with chronic heart failure in comparison with other classical markers such as clinical established parameters but also biological markers: NT-proBNP, hs-cTnT alone or in combination." (PMID 27311068, 2016). "Circulating levels of CRP have been shown to increase in patients suffering from acute MI or chronic heart failure." (PMID 28190984, 2016). "Further risk factors identified by individual studies included male, an additional diagnosis of chronic heart failure and a raised CRP." (PMID 25854831, 2015). "C-reactive protein is an independent predictor of adverse outcomes in patients with acute or chronic heart failure." (PMID 26506526, 2015). "For inflammatory factors such as C-reactive protein (CRP) and cytokines (tumour necrosis factors, interleukin-6), higher levels have been observed in elderly subjects and in subjects at higher risk of chronic heart failure (CHF)." (PMID 16283930, 2005).
congestive heart failure (continued). "This could be shown for C-reactive protein, as higher levels are related to a worse prognosis in patients with acute and chronic heart failure." (PMID 40429565, 2025). "CRP is a marker of chronic systemic inflammation and could be directly involved in congestive heart failure (CHF)." (PMID 37919409, 2023). "When comparing baseline characteristics between survival and mortality group, there was no statistically significant between-group difference, except in heart rate, systolic blood pressure, oxygen saturation, CRP and presence of chronic heart failure (p < 0.05)." (PMID 37109615, 2023). "The combined assay of NT-proBNP, MR-proADM, and CRP could be helpful in accurately identifying congestive heart failure." (PMID 37511766, 2023). "The C-reactive protein-to-albumin ratio (CAR), a marker of inflammation and nutritional status (calculated as C-reactive protein [CRP]/albumin [ALB]), is associated with increased mortality in congestive heart failure (CHF)." (PMID 40776958, 2025). "Serum DLL-1 levels are significantly higher in patients with chronic heart failure than in healthy individuals, and DLL-1 levels have been significantly associated with diastolic dysfunction, decreased exercise capacity, increased levels of C-reactive protein (CRP), and adverse." (PMID 36036015, 2022). "Interestingly, n-3 PUFAs supplementation in the form of capsules (2g n-3 PUFAs per day/3 months) significantly decreased IL-6 and TNFα levels in patients with chronic heart failure, and CRP and IL-6 levels were significantly decreased in overweight women with an inflammatory phenotype." (PMID 34440006, 2021). "Phenotype A exhibited elevated levels of amylase, lipase, BUN, creatinine, sodium, potassium, CRP, PCT, glucose, triglycerides, and the highest proportion of congestive heart failure and renal disease, categorizing it as the “hyperinflammatory subphenotype”." (PMID 40467599, 2025). "Mortality was significantly higher in patients who had recently received chemotherapy (67.7% vs 44.8%, p = .039), a history of congestive heart failure (CHF)(p = .04), higher levels of CRP (p = 0.048) and/or PCT(p<0.04) or were tachypneic in the ED (P = 0.016)." (PMID 36701309, 2023). "A report encompassing 2184 patients with previous MI from the Chronic Heart Failure Registry and Analysis in the Tohoku district-2 (CHART-2) study focused on the importance of persistently elevated CRP levels." (PMID 36556477, 2022). "CRP is a useful prognostic indicator in patients with ACS, as elevated CRP levels are independent predictors of cardiac death, AMI, and congestive heart failure." (PMID 32016113, 2020). "Patients in chronic heart failure also exhibit higher levels of pro-inflammatory cytokines including TNF-α, IL-6, IL-1β, and C-reactive protein." (PMID 32125488, 2020). "The CONUT score has been reported to exhibit a significant positive correlation with CRP and a significant negative correlation with hemoglobin in patients with chronic heart failure." (PMID 39656282, 2025). "On the other hand, Mao et al33 in 2017 reported that forest bathing reduced the level of IL-6, but not TNF-α and CRP in elderly patients with chronic heart failure." (PMID 40673365, 2025). "S2 Table in S1 File shows the characteristics associated with composite outcomes including male sex, hypoxia, elevated respiratory rate, history of congestive heart failure, and elevated WBC, troponin, D-dimer, and hs-CRP as well as low platelet count (p<0·01)." (PMID 35259186, 2022). "For instance, CRP POCT might provide the physician with valuable information for the differential diagnosis between LRTI and congestive heart failure." (PMID 32103747, 2020). "In patients with congestive heart failure and in heart transplant recipients, bolus consumption of 40 g dark or cocoa-free chocolate did not change CRP." (PMID 27240397, 2016).
congestive heart failure (continued). "In patients suffering from CAD and congestive heart failure, daily ingestion of flavanol-rich chocolate or cocoa for 28–42 days did not change CRP, P-selectin, E-selectin, ICAM-1, or VCAM-1." (PMID 27240397, 2016). "Nevertheless, intervention studies of healthy post-menopausal women and patients with congestive heart failure failed to see changes in CRP concentrations after vitamin D supplementation." (PMID 18652680, 2008). "CRP, albumin and hemoglobin were evaluated in 119 patients, divided into two disease groups, hematological (ones with diagnosis of non-Hodgkin lymphoma or Hodgkin disease) and non-hematological (solid tumor patients and patients with chronic heart failure)." (PMID 23294910, 2013). "hsCRP: high sensitivity C-reactive protein; NLR: Neutrophil Lymphocyte Ratio; VTE: Venous Thromboembolism; MVO: Microvascular Obstruction; WBC: White Blood Cells; CRP: C-reactive protein; CHF: Congestive Heart Failure; USA: United States of America; TNF-α: Tumor Necrosis Factor-alpha." (PMID 37859889, 2023). "Laboratory evaluation revealed elevated N-terminal pro-brain natriuretic peptide (NT-pro BNP), troponin I, creatine kinase (CK), and C reactive protein (CRP), and transthoracic echocardiogram showed congestive heart failure (CHF) with a preserved ejection fraction (HFpEF)." (PMID 36605067, 2022).
delirium (168 papers, 2008 to 2026). A disorder characterized by confusion; inattentiveness; disorientation; illusions; hallucinations; agitation; and in some instances autonomic nervous system overactivity. "Of these, 21 studies comprising 5,006 patients examined the association of CRP with delirium using continuous data, while 11 studies involving 3,996 patients employed categorical data by dividing patients into high and low groups based on the CRP value." (PMID 41695631, 2026). "The observed association between elevated CRP and delirium in our cohort reinforces the role of systemic inflammation as a key mechanism." (PMID 41303282, 2025). "Previous studies have linked elevated perioperative CRP to delirium severity and duration, especially in cardiac surgery and intensive care settings." (PMID 41303282, 2025). "A recent systematic review also links increased perioperative CRP levels to a high delirium risk, supporting our inclusion of hsCRP as a predictor." (PMID 39813086, 2025). "The primary objective of this study was to assess the association between CRP (C-reactive protein) levels and the incidence and severity of postoperative delirium in patients undergoing cardiac and neurosurgical procedures." (PMID 41303282, 2025). "Persistently elevated CRP levels beyond postoperative day 4 are strongly associated with higher delirium risk, especially in APOE ε4 allele carriers, suggesting a genetic predisposition to inflammation-driven cognitive impairment." (PMID 40529139, 2025). "Previous systematic reviews and meta-analyses have predominantly focused on a limited set of inflammatory and neuronal injury-related biomarkers, such as IL-6, CRP, cortisol, and S100β, in relation to delirium risk." (PMID 40889075, 2025). "Studies have shown elevated CRP levels have also been associated with delirium and psychological disorders even in the absence of a TBI event." (PMID 39554848, 2024). "Age, short nighttime sleep, general anesthesia, high intraoperative blood loss, hypoxemia, and high CRP levels are all independent risk factors for delirium after hip arthroplasty." (PMID 38952533, 2024). "Ma, etc. study indicated the postoperative levels of CRP are associated with the incidence and severity of delirium." (PMID 39839309, 2024). "The CRP plays a novel role in the pathophysiology of delirium as it is associated with stress response, and inflammation and has a role in neurotransmitter activities." (PMID 39700095, 2024). "This emphasizes the necessity of identifying TBI patients at high risk for delirium and psychological problems based on early CRP concentrations." (PMID 39554848, 2024). "Age, short nighttime sleep, general anesthesia, high intraoperative blood loss, hypoxemia, and high CRP levels are independent risk factors for delirium after hip arthroplasty." (PMID 38952533, 2024). "Age, nighttime sleep time, anesthesia method, intraoperative blood loss, hypoxemia, and CRP level were all independent risk factors for delirium after hip arthroplasty (P<0.05), Table-II." (PMID 38952533, 2024). "Age, nighttime sleep, anesthesia method, intraoperative blood loss, hypoxemia, and C-reactive protein (CRP) level were all risk factors of delirium after the hip arthroplasty (P<0.05)." (PMID 38952533, 2024). "Our study found that older age, shorter nighttime sleep, general anesthesia, high intraoperative blood loss, hypoxemia, and high CRP levels are all important risk factors for delirium after hip arthroplasty." (PMID 38952533, 2024). "Our findings add nuance to prior biomarker work showing greater quartiles of CRP, IL-8, and S-100β measured at delirium onset were associated with increased in-hospital mortality." (PMID 37656731, 2023). "High serum IL-6 or C-reactive protein (CRP) levels were reported to increase the risk of postoperative delirium (POD) in three meta-analyses of cohort or case–control studies." (PMID 37649721, 2023).
delirium (continued). "Eighteen studies investigated the association between CRP serum concentration at hospital admission and delirium during hospitalization." (PMID 37360340, 2023). "There was an association between delirium and increased CRP levels (OR 1.14; 95% CI 1.02 to 1.30, p = 0.049)." (PMID 38100603, 2023). "As a predisposing factor, the preoperative plasma homocysteine modified the established association between the postoperative plasma CRP, a precipitating factor, and the incidence of postoperative delirium." (PMID 36212043, 2022). "Pending validation studies, these data suggest that preoperative plasma concentration of homocysteine modifies the established association between postoperative plasma concentration of CRP and postoperative delirium incidence." (PMID 36212043, 2022). "The association between the incidence of postoperative delirium and the preoperative homocysteine, postoperative C-reactive protein, or their interaction." (PMID 36212043, 2022). "Higher age, longer hospital stays, lower oxygen saturation, lower lymphocytic count, and higher C-reactive protein (CRP) values were significantly associated with delirium versus other psychiatric diagnoses." (PMID 35836717, 2022). "A recent study demonstrated the interaction between gene Apolipoprotein E (a predisposing factor) and postoperative CRP (a protein and precipitating factor) on postoperative delirium." (PMID 36212043, 2022). "Studies have been performed to support the association of CRP with pre-operative and postoperative delirium." (PMID 36675728, 2022). "Nevertheless, the present study showed that the preoperative plasma concentrations of homocysteine modified the established association between postoperative plasma concentration of CRP and postoperative delirium incidence." (PMID 36212043, 2022). "In particular, NLR and CRP were associated with an increased risk of delirium per ten units of measurement by 45% and 126%, respectively." (PMID 35204633, 2022). "In our population, delirium was associated with a range of variables, including hypoxia, older age, elevated CRP, and a prolonged hospital length of stay compared to patients with other psychiatric diagnoses." (PMID 35836717, 2022). "As such, the present study extends previous research that NLR in peripheral blood and high serum and CSF CRP are consistently reported as biomarkers or predictive risk factors of post-operative delirium." (PMID 35641947, 2022). "Specifically, participants with lower preoperative homocysteine demonstrated a stronger association between postoperative CRP and postoperative delirium incidence than participants with higher levels of preoperative homocysteine." (PMID 36212043, 2022). "Comparing the findings from this review to other causes of delirium makes clear that in delirium from other causes mostly biomarkers regarding inflammatory pathways are involved (e.g., IL-6, CRP, Corsitol, TNF-alpha)." (PMID 36230916, 2022). "Excessive hemorrhage, longer ICU stay, lower preoperative albumin and hemoglobin levels, and higher postoperative CRP levels were also risk factors for postoperative delirium in oral cancer surgery patients." (PMID 35465424, 2022). "The association between the severity of postoperative delirium and the preoperative homocysteine, postoperative C-reactive protein, or their interaction." (PMID 36212043, 2022). "Consistently, we confirmed that the high postoperative plasma concentration of CRP was associated with postoperative delirium incidence and severity." (PMID 36212043, 2022). "C-reactive protein (CRP), one of the most common markers of systemic inflammation, has been recognized as an independent risk factor for delirium after vascular surgery and hip surgery." (PMID 36051706, 2022). "C-reactive protein (CRP) has been linked to delirium in individuals with critical illness and other populations." (PMID 35773648, 2022).